NRP1 (neuropilin 1)
Diseases named in the same sentence as NRP1 in open-access papers (continued):
Sharing a sentence is not in itself a finding about the gene and the disease.
pancreatic ductal adenocarcinoma (16 papers, 2016 to 2023). An infiltrating adenocarcinoma that arises from the epithelial cells of the pancreas. "For one, iRGD administration is used to enhance transcytosis of silicasome-loaded irinotecan through the neuropilin-1 (NRP-1) pathway for the treatment of pancreatic ductal adenocarcinoma (PDAC)." (PMID 37273793, 2023). "Another study showed that neuropilin-1 can actively bind TGFβ1 and is involved in epithelial-to-mesenchymal transition processes in pancreatic ductal adenocarcinoma." (PMID 36672243, 2023). "Remarkably, anti-PGPQLR373 antibodies capable of blocking the binding of CgA1-373 to neuropilin-1 can reduce the growth of pancreatic ductal adenocarcinoma in mice, which implicates an important role of neuropilin-1 as mediator of these effects." (PMID 36559048, 2022). "In pancreatic ductal adenocarcinoma, microvessel density was significantly higher in the tumors with high NRP-1 expression than that in the tumors with low NRP-1 expression." (PMID 33884469, 2021). "Previous studies have shown that the silencing of NRP1 in pancreatic ductal adenocarcinoma has multiple cellular and molecular antitumor effects." (PMID 32472711, 2020). "A positive correlation between NRP-1 levels, EndMT markers and profibrotic gene expressions has been reported in pancreatic ductal adenocarcinoma tissues." (PMID 32664340, 2020). "We recently demonstrated that VEGFR2/NRP1 complexes are formed in human pancreatic ductal adenocarcinoma, and the presence of VEGFR2/NRP1 trans complexes was identified as an independent marker of improved overall survival." (PMID 31880322, 2020). "In pancreatic duct adenocarcinoma as well as in murine fibrosarcoma, formation of such NRP1/VEGFR2 trans-complex reduces vessel branching and proliferation of tumor cells." (PMID 30717262, 2019). "Pancreatic ductal adenocarcinoma (PDAC) strongly expressed NRP1 on both tumor cells and endothelial cells, in contrast to other common cancer forms." (PMID 30027561, 2018). "Blocking the interaction between VEGF165 and NRP1 with an anti‐NRP1 heptapeptide A7R (ATWLPPR), significantly reduced VEGFR signaling and tumor growth in a pancreatic ductal adenocarcinoma mouse model." (PMID 33373502, 2021). "The study, examining Nrp1 and VEGFR2 interactions in pancreatic ductal adenocarcinoma (PDAC) patients, revealed that the trans configuration of Nrp1 could lead to lack of engagement of endothelial VEGFR2 through possible disrupted signaling pathways, such as in extracellular regulated kinase (ERK)." (PMID 36203599, 2022).
Sepsis (16 papers, 2015 to 2025). Sepsis is defined as life-threatening organ dysfunction caused by a dysregulated host response to infection. "Nrp1 has been previously proposed as a cell marker for thymic-derived Treg cells; but its expression has also been described on T cells during allogeneic skin graft rejection, sepsis, IL-10 deficiency, and anti-tumor immune responses." (PMID 31068948, 2019). "In the context of sepsis, NRP-1 has been shown to stabilize regulatory T cells (TReg), promoting the release of immunomodulatory cytokines such as IL-4, IL-10, and TGF-β." (PMID 40733612, 2025). "NRP1 is known to be overexpressed by macrophages in acute and chronic inflammation-related diseases (sepsis, type II diabetes, and metabolic syndrome, etc.)." (PMID 37421595, 2023). "Here, we report that Nrp‐1 and TGF‐β1 stimulate the stability of CD4+CD25+ Tregs in the presence of LPS and that Nrp‐1 contributes to the activity of recombinant TGF‐β1 by the regulation of TGF‐β1/Smads cell signaling in sepsis." (PMID 34758202, 2022). "This study demonstrates that Nrp‐1 knockdown lessens the viability of CD4+CD25+ Tregs during sepsis depending upon its grade and time." (PMID 34758202, 2022). "They showed that miR-21a-3p levels in plasma and TECs increased during sepsis by the internalization of plasmatic Ago2, which binds miR-21a-3p mediated by membrane Nrp-1." (PMID 36012630, 2022). "In the current study, we first reported that sepsis per se markedly promoted the expression of Nrp-1 on CD4+CD25+Tregs in a grade- and time- dependent manner." (PMID 27835904, 2016). "From 12 to 72 hrs, compared with the control and sham groups, the expression of Nrp-1 on CD4+CD25+Tregs was significantly enhanced by sepsis (P<0.01)." (PMID 27835904, 2016). "Given the involvement of NRP-1 in the immune system and regulation of vascular permeability, this study aims to investigate the role of its antagonist, sNRP-1, in critical illness and sepsis and assess its potential as a biomarker in this setting." (PMID 38791476, 2024). "miR-128-3p targets neuropilin-1 and promotes inflammatory responses in sepsis-induced AKI." (PMID 39715172, 2024). "Moreover, it has been found that miR-128-3p enhances inflammation by repressing NRP1 levels in sepsis-induced AKI." (PMID 34250012, 2021). "In fact, in cecal ligation and puncture as well as intraperitoneal LPS models of sepsis using myeloid cell-specific NRP1-knockout mice there is increased production of pro-inflammatory cytokines (iNOS, TNF-α, IL-6) in peritoneal lavage and serum and higher mortality compared with wild-type mice." (PMID 34012455, 2021). "Taken together, it can be concluded from our results that Ago2 binding miR-21a-3p from septic plasma can be actively internalized by TECs via Nrp-1 mediated cell internalization, and this mechanism is crucial for the rise of intracellular miR-21a-3p content of TECs during sepsis." (PMID 32923478, 2020). "Moreover, membrane Nrp-1 expression of TECs was increased significantly during sepsis and Nrp-1 knockdown also mitigated the rise of both the intracellular Ago2 and miR-21a-3p levels in TECs incubated with septic plasma." (PMID 32923478, 2020). "This suggested that Nrp-1 is the primary receptor of tuftsin on Tregs in the environment of sepsis." (PMID 27835904, 2016). "However, in a few studies researchers have examined the role and associated mechanisms of Nrp‐1 in immunosuppression and whether it affects the cell viability of CD4+CD25+ Tregs in sepsis." (PMID 34758202, 2022). "Our results suggest that Nrp‐1 is beneficial for TGF‐β1 to enhance the stability of CD4+CD25+ Tregs, and may represent a novel therapeutic target with the potential to improve the CD4+CD25+ Tregs‐related primary negative immunoregulation associated with the TGF‐β1/Smads signaling pathway in sepsis." (PMID 34758202, 2022).
Sepsis (continued). "According to the results, Nrp‐1 mediates TGF‐β1 to improve the stability of regulatory CD4+CD25+ T cells and maybe a possible therapeutic target with the ability to improve the CD4+CD25+ Tregs associated negative immunoregulation that is related to the TGF‐β1/Smads cell signaling during sepsis." (PMID 34758202, 2022). "On the contrary, NRP1, which has been identified as a co-receptor for SEMA3A, is shown to down-regulate the systemic inflammatory response of sepsis." (PMID 34012455, 2021). "Nevertheless, the impact of sepsis on the serum concentration of tuftsin and the expression of Nrp-1 on CD4+CD25+Tregs, as well as the potential therapeutic value and mechanisms of tuftsin in sepsis remains to be elucidated." (PMID 27835904, 2016). "However, there is a lack of data on NRP-1 in human sepsis, despite efforts to understand its role in sepsis and its connection to kidney failure." (PMID 38791476, 2024). "Nrp-1highTregs might reveal primary negative immunoregulation in sepsis, Nrp-1 could represent a new potential therapeutic target for the study of immune regulation in sepsis." (PMID 27835904, 2016). "Nrp-1 had the ability to preserve the negative immunoregulation of Tregs in sepsis." (PMID 27835904, 2016). "Moreover, Nrp‐1highCD4+CD25+ Tregs revealed primary negative immunoregulatory activity in reaction to sepsis, while administration of a recombinant version of Nrp‐1 polyclonal antibody markedly lowered the demethylation of Foxp3‐TSDR in a dose‐dependent manner under LPS stimulation." (PMID 34758202, 2022). "Our previous study suggested that recombinant Nrp-1 polyclonal antibody could decrease the demethylation of Foxp3-TSDR in the presence of LPS, thus, Nrp-1 could represent a new potential therapeutic target, at least via regulating the stability of Tregs, for the study of immune regulation in sepsis." (PMID 27835904, 2016).
atherosclerosis (15 papers, 2019 to 2026). A disease characterized by the build-up of fatty material and calcium deposition in the arterial wall resulting in partial or complete occlusion of the arterial lumen. "In accordance, Gaddis and colleagues observed an increased frequency of Nrp-1+CD4+ effector T cells in a model of atherosclerosis that was also associated with an activated phenotype and ablation of Nrp-1 on T cells led to a better disease outcome." (PMID 38019895, 2023). "Together, our data point to actin filament organization and NRP1 expression in macrophages as potentially important targets, the alteration of which may be causally linked to iWD-dependent acceleration of atherosclerosis." (PMID 39231480, 2024). "A strong role of NRP-1 has been described in vascular biology, including angiogenesis and the development of atherosclerosis." (PMID 38638882, 2024). "NRP1 has been shown to have a role in mitochondrial dysfunction, atherosclerosis, and neurodegeneration as well as in brain microvascular endothelial inflammation and blood–brain-barrier function." (PMID 37280551, 2023). "Downregulated miR-199 also increased levels of atherosclerosis-related biomarkers (Angiogenin, Galactin-3 and Neuropilin-1) in heart failure patients with peripheral artery disease." (PMID 36071532, 2022). "In addition, recent evidence shows that NRP1 at the plasma membrane regulates mechanosensing and AJ signalling, suppressing signals involved in inflammation and atherosclerosis." (PMID 38323651, 2024). "Nrp1, a type I transmembrane protein, is also a double-edged sword in atherosclerosis." (PMID 38164188, 2024). "As the recruitment of leukocytes to endothelium is an initial stage in inflammatory diseases, including atherosclerosis, our results suggest that NRP1 could potentially be modulated to maintain vascular health." (PMID 38994453, 2024). "Taken together, our data implicate NRP1 as part of a biological pathway that affects the arterial macrophage cytoskeleton and becomes altered in response to early intermittent hyperlipidaemia, leading to acceleration of atherosclerosis." (PMID 39231480, 2024). "In our study, NRP1 was identified as a disease-characteristic gene of atherosclerosis, which indicates that NRP1High M2 macrophages may be a major risk factor for the formation and stability of atherosclerosis." (PMID 37421595, 2023). "However, the role of myeloid NRP1 in atherosclerosis is unclear." (PMID 39231480, 2024). "Our data suggest that promoting NRP1-dependent signaling could be particularly relevant in age-related diseases characterized by increased oxidative stress or by deregulation of iron metabolism such as atherosclerosis, vascular dementia, and Alzheimer disease." (PMID 30623799, 2019). "From these results and in vivo data, they concluded that Nrp-1 aids in the migration of CD4+ effector T cells into the aortic tissue and draining lymph nodes and worsen the outcome of atherosclerosis." (PMID 38019895, 2023). "This correlates with increased atherosclerotic plaque in an ApoE atherosclerosis mouse mutant lacking NRP1 expression in the endothelium, indicating a key anti-inflammatory and atheroprotective role of endothelial NRP1." (PMID 38323651, 2024).
Autoimmunity (14 papers, 2012 to 2025). The occurrence of an immune reaction against the organism's own cells or tissues. "In the sanroque mouse model of autoimmunity, massive Tfh differentiation and activity is associated with increased Nrp1 expression at the mRNA level." (PMID 24386482, 2013). "NRP1 may also function to suppress autoimmunity, as CD4+ loss of NRP1 in a mouse model of multiple sclerosis skews inflammatory populations to a TH-17 phenotype and reduces Treg populations, worsening autoimmune disease progression." (PMID 32914058, 2018). "The unusual NRP1+ conventional Th cells sharing a surface phenotype with Treg have not been previously reported in systemic autoimmune disease or target organ autoimmunity." (PMID 36069030, 2022). "At any rate, conditional Nrp1 knockout in murine T cells results in poor Treg function and increased autoimmunity." (PMID 22948112, 2012). "We also observed a slight increase in NRP1+ cells among Foxp3− Th cells in MRL mice at 20–22 weeks, which may relate to the onset of the weaker systemic autoimmunity associated with non‐LPR MRL mice." (PMID 36069030, 2022). "Overall, these data indicate that NRP1 expression by non‐Treg Th cells in autoimmunity may extend further than PD‐1+ Tfh/Tph cells in systemic autoimmune disease." (PMID 36069030, 2022). "Very importantly, Nrp1 deficiency in Tregs would not induce any autoimmune or inflammatory disease of host, indicating that Neuropilin-1 is dispensable for prevention of autoimmunity or maintenance of immune homeostasis." (PMID 29225597, 2017). "The deficiency of Nrp-1 on Tregs fails to limit autoimmunity and induces autoimmune diseases." (PMID 35155237, 2022). "Importantly, Nrp-1 is required for Treg to limit anti-tumor immune responses and to cure established inflammatory colitis, but is dispensable for the suppression of autoimmunity and maintenance of immune homeostasis." (PMID 35603221, 2022). "Considering the involvement of TIGIT and NRP1 in T cell exhaustion and chronic inflammation, CUR’s modulation of this axis offers new perspectives for therapeutic intervention in other chronic autoimmune or inflammatory diseases characterized by T cell dysfunction." (PMID 41465029, 2025). "This increase in NRP1 expression in non‐Treg Th cells is not observed in standard mice that are not prone to autoimmunity when the steady state is maintained during aging." (PMID 36069030, 2022). "This milestone discovery makes Neuropilin-1 one potential therapeutic target, which could restrain Treg-mediated antitumor effects without inducing autoimmunity." (PMID 29225597, 2017). "Possible combination blockades of IL10 and Nrp-1 via bispecific antibodies or soluble antagonists may one day be a viable therapeutic strategy to limit tumor-induced tolerance without evoking autoimmunity." (PMID 27075020, 2016). "The maintenance of immune homeostasis and the prevention of autoimmunity may not require Nrp-1 signaling." (PMID 27075020, 2016). "Slight increases in NRP1+ conventional Th cells are also observed in MRL mice by 20 weeks that may occur at the same time as early autoantibody increase seen even without the LPR mutation, although full autoimmunity does not become established in this strain until 1–2 years of age." (PMID 36069030, 2022). "Recently, a Sema4A-neuropilin-1 (Sema4A-NRP1) axis was reported to maintain T regulatory (Treg) cell stability, highlighting this pathway as a potential therapeutic target that could limit Treg-cell-mediated tumor-induced tolerance without inducing autoimmunity." (PMID 26303122, 2015).
brain tumor (14 papers, 2015 to 2025). "It will be interesting to test this possibility by treating mice harboring Nrp1-deficient brain tumors with inhibitors of the VEGF-A pathway." (PMID 28938007, 2017). "Finally, this review suggests a relevant role for NRP1 in pediatric brain tumors progression and identifies it as a potential diagnostic or therapeutic target to improve survival and life quality of these young patients." (PMID 34277411, 2021). "Furthermore, NRP1 also appears to be implicated in treatment resistance of pediatric brain tumors." (PMID 34277411, 2021). "While SEMA3F suppresses U87 migration via the NRP2/PLXNA1 receptor complex, SEMA3A suppresses brain tumor stem cell proliferation but enhances migration through NRP1/PLXNA1 complex, and PLXNA1-knockdown reduced the growth of GBM in an mice model." (PMID 40533501, 2025). "This evidence supports the view that NRP1 is a potential prognostic biomarker and therapeutic target in brain tumors." (PMID 37894289, 2023). "The example of NRP1 highlights the potential of regulators of nervous system development as biomarkers and molecular targets in brain tumors." (PMID 37894289, 2023). "Increasing evidence indicates that neuropilins, particularly neuropilin-1 (NRP1), can affect the progression of different types of brain tumors, and modification of NRP1 activity has been investigated as an experimental therapeutic approach." (PMID 37894289, 2023). "Analysis of pediatric brain tumors database shows a significant correlation between NRP1 and PDL-1 for three tumor types, such as HGGs or LGGs, as well as EPNs, and a weak correlation for MBs." (PMID 34277411, 2021). "NRP1 expression in brain tumors was further examined in light of the promising historical results for radiolabeled Cltx in this indication." (PMID 31208428, 2019). "Neuropillin-1 (or NRP1), a transmembrane receptor expressed by various cells in the body, plays a role in brain tumor progression through its expression in microglia." (PMID 31824268, 2019). "Next, we intracranially implanted LN229 cells to analyze Nrp1-dependent brain tumor growth and progression." (PMID 28938007, 2017). "To determine functions for Nrp1 in GBM we first analyzed levels of Nrp1 gene expression in human brain tumor samples by querying The Cancer Genome Atlas (TCGA) GBM database." (PMID 28938007, 2017). "Indeed, several research teams have noted that, when NRP1 is overexpressed in tumor tissues, such as pediatric brain tumors, the prognosis for those patients was poor in contrast to the patients without an overexpression of the receptor." (PMID 34277411, 2021). "Furthermore, analysis of pediatric brain tumors databases shows a significant correlation between NRP1 and CD15 for the four analyzed tumor types." (PMID 34277411, 2021). "Therefore, we propose that the increased sizes of orthotopic brain tumors that lack Nrp1 are, in part, the outcome of increased VEGF-A-driven angiogenesis, enabling more rapid GBM progression." (PMID 28938007, 2017). "Although the two studies revealed different signaling mechanisms downstream of Nrps focusing on different subgroups of MBs, both studies highlight the involvement of Nrps in the development of MB, and highlight Nrp1 as a promising therapeutic target for this devastating brain tumor." (PMID 26371509, 2015). "Although the roles of NRP1 in tumor angiogenesis, tumor microenvironment, as well as its possible targeting in tumor progression, have recently been reviewed elsewhere, in this review, we summarize the up-to-date knowledge on NRP1 and its role in pediatric brain tumors progression." (PMID 34277411, 2021). "We propose a model in which Nrp1 promotes interactions between GBM cells and blood vessels in the brain tumor microenvironment via the TGFβ pathway as well as VEGF-A." (PMID 28938007, 2017). "An immunostaining study found that GBM CD133-expressing brain tumor stem cells (BTSCs) highly express NRP1, whereas differentiated GBM cells do not." (PMID 37894289, 2023).
brain tumor (continued). "We hypothesized that Sema3A directly inhibits brain tumor stem cell (BTSC) proliferation and drives invasion via Neuropilin 1 (Nrp1) and Plexin A1 (PlxnA1) receptors." (PMID 33302912, 2020).